CD47 (CD47 molecule)
Diseases named in the same sentence as CD47 in open-access papers (continued):
Sharing a sentence is not in itself a finding about the gene and the disease.
tumor (continued). "Overall, these early trial results indicate that CD47/SIRPα blockade was well tolerated and elicited anti-tumor activity in multiple malignancies." (PMID 37958404, 2023). "CD47-overexpressed hybrid therapeutic nanovesicles exhibited long blood circulation and improved the macrophage-mediated phagocytosis of tumor cells." (PMID 37242738, 2023). "aCD47 recognizes tumor cells by identifying the CD47 on their surface and thereby actively targets the tumor." (PMID 37475025, 2023). "Signal regulatory protein alpha (SIRPα) is a receptor expressed on macrophages that can interact with CD47, which is upregulated on some tumor cells, and thus transmit a “don’t eat me” signal." (PMID 36960057, 2023). "A novel hGLV EV overexpressing CD47 has been found to enhance macrophage-mediated tumor cell phagocytosis by blocking CD47 signaling in tumor cells." (PMID 38087360, 2023). "It has been reported that inflammation promoted the expression of αL and αX integrins in macrophages, thereby inhibiting CD47 overexpression in tumor cells, which prevented checkpoint SIRPa-CD47 from exerting anti-phagocytic effects." (PMID 37047140, 2023). "Most tumors contain the surface receptor CD47 that interacts with the signal-regulating protein α (SIRPα) on phagocytes and reduces the ability of macrophages to phagocytize tumor cells." (PMID 37373342, 2023). "Numerous studies have demonstrated CD47's overexpression in various tumor types, including myeloma, leiomyosarcoma, acute lymphocytic leukemia, non-lymphoma, Hodgkin's breast cancer, osteosarcoma, and head and neck squamous cell carcinoma." (PMID 37822610, 2023). "In contrast, expression of CD47 K99/102R increased CD47 expression with correspondingly decreased macrophage phagocytosis of the tumor cells and promoted tumor growth." (PMID 37541303, 2023). "PD-L1/L2 inhibition, along with CD47 and PD-L1 antibodies, synergistically enhances anti-tumor immunity, offering potential breakthroughs in cancer therapy." (PMID 38258072, 2023). "Given the weak pH-dependence of BC31M5, BC31M5 still exhibits higher relative intratumoral accumulation than Hu5F9, highlighting the apparently advantage of tumor selectivity for anti-CD47 therapy." (PMID 36650558, 2023). "We set out to create a BsAb targeting both human PD1 and CD47 in order to create a novel biologic with enhanced anti-tumor activity and reduced hemotoxicity based on rational design." (PMID 37012357, 2023). "In acidic TME, benzoic amine bonds cleave and release SIRPα and anti-CD47, enhancing tumor cell phagocytic elimination." (PMID 37345176, 2023). "Functional studies in A549 demonstrated that CD47 promotes invasion and migration in vitro as well as tumor growth and metastasis in vivo." (PMID 37958404, 2023). "The frequency of CD47+ cells was higher within the double positive (EpCAM+CD24+) tumor cell population than in the EpCAM+CD24- tumor cell fraction in both the spheroids and the tumoroids." (PMID 37876933, 2023). "In summary, the applications of CD47-SIRP-based therapy in the treatment of non-neoplastic diseases are still in early stage." (PMID 38125492, 2023). "The binding of SIRPA to CD47 triggers inhibitory pathways in some cancers, ultimately leading to the immune escape of tumor cells." (PMID 38228050, 2023). "While we show that the CD47/SIRPα axis is a key regulator in tumor growth, tumors frequently exploit multiple mechanisms to avoid immune surveillance." (PMID 37444515, 2023). "This inequivalent binding affinity design makes 6MW3211 preferentially bound to PD-L1 on tumor cells followed by disrupting the interaction of CD47/SIRPα." (PMID 36593962, 2023). "Alternatively, it has been shown that blocking the CD47-SIRPα signaling pathway can collaborate with tumor-specific antibodies to enhance the clearance of tumor cells." (PMID 37345054, 2023). "Previous studies have been suggested that CD47 affected the biological behaviour like proliferation, migration and invasion in various tumor types." (PMID 37171006, 2023).
tumor (continued). "CD47 expression on stromal cells contributes not only contribute to angiogenesis and tumor growth but also to immune evasion." (PMID 38188674, 2023). "After anti-CD47 treatment, tumor cells with MHC-I high are more resistant to phagocytosis by macrophages than those with MHC-I low expression." (PMID 36882399, 2023). "In summary, CD47-targeted therapies offer a promising opportunity to enhance anti-tumor immunity and improve clinical outcomes in cancer patients." (PMID 38188674, 2023). "Similar to Cd47 knockdown, we observed that miR-34a overexpression strongly inhibited CD47 protein levels and promoted tumor phagocytosis by M1 macrophages; cotreatment with AAV-CD47 in mice completely reversed the effect of miR-34a." (PMID 36413402, 2023). "For example, the monoclonal antibody KWAR23, which binds human SIRPα with high affinity and disrupts its binding to CD47, has been shown to be a promising candidate in therapy, though in combination with tumor-opsonizing monoclonal antibodies." (PMID 37999184, 2023). "Taken together, these data suggested that CD47 was involved in KRAS-driven tumor progression by restraining the antitumorigenic properties of macrophages." (PMID 36413402, 2023). "CD47 expressed on tumor cells binds to signal regulatory protein alpha on macrophages, initiating inhibition of phagocytosis." (PMID 36598153, 2023). "The combination of CD47 knockout and IL-12 production synergistically enhanced macrophage-mediated phagocytosis for tumor immunotherapy." (PMID 38258073, 2023). "In the present study, we aimed to overcome this dilemma by improving the tumor selectivity of anti-CD47 antibodies, and our approach was to exploit the known acidic microenvironment of solid tumors." (PMID 36650558, 2023). "Drugs targeting CD47 can enhance macrophage phagocytosis in the special environment of tumor tissue and promote macrophage recruitment to tumor by directly blocking the binding of SIRPα to CD47." (PMID 37484024, 2023). "Considering the relevance of the CD47/SIRPα axis in tumor progression, including under (chemo)-therapeutic pressure, several novel studies have demonstrated the potential of CD47-based combination therapies in different types of cancer." (PMID 37153563, 2023). "CD47 is frequently overexpressed on tumor cells and plays a key role in tumor escape by binding to SIRPα and sending macrophages a ‘don't eat me’ signal." (PMID 36911370, 2023). "More importantly, the large number of RBCs in the body will be the best cover for tumor cells, as drugs targeted to CD47 will be depleted by RBCs before they reach the tumor cells." (PMID 37171006, 2023). "Our study shows that an oncolytic Myxoma virus (MyxV) encoding CD47 and IFN-γ is effective against cancer cells and enhances anti-tumor immunity in murine cancer models." (PMID 37835397, 2023). "Tumor cells and atherosclerotic necrotic cores with increased CD47 expression escape efferocytosis, contributing to disease progression." (PMID 37368493, 2023). "The study of HER2/SIRPα (CD47) dual antibody suggests that CD47 antibody mediates the anti-tumor effect of ADCP to enhance HER2 antibody." (PMID 37007133, 2023). "AMG 510 treatment for 8 days significantly suppressed tumor growth, inhibited KRAS activity, STAT3 phosphorylation, and CD47 expression, and stimulated miR-34a expression in tumor tissues." (PMID 36413402, 2023). "The “don’t eat me” signal transmitted by CD47 on tumor cells contributes to the inhibition of their phagocytosis by interacting with signal regulatory protein-alpha (SIRPα) displayed by macrophages." (PMID 37476156, 2023). "Immunotherapies, including ICIs, CAR T-cell therapy, and antibody-based therapies, are being developed to target CD47 or its interactions with other TME components to enhance anti-tumor immunity and improve clinical outcomes." (PMID 38188674, 2023). "The combination of a FAO inhibitor and an anti-CD47 antibody also improved tumor treatments in a mouse model for GBM relapse after radiotherapy." (PMID 37322433, 2023).
tumor (continued). "This “imbalanced” design was anticipated to block CD47 on CD47+/PD-L1+ tumor cells more specifically than standard anti-CD47 while reducing on-target damage in normal tissues." (PMID 37345054, 2023). "The improved priming administration scheme of anti-CD47 molecules in combination with other agents promoting the expression of the prophagocytic signal on tumor cells has been used to avoid this adverse effect and demonstrated effective results." (PMID 36575242, 2023). "It appears that the sensitivity (93%) and specificity (100%) of tumor targeting by ICG-anti-CD47 is irrelevant to the subtype of tumor." (PMID 36937442, 2023). "Pre-injecting cationized mannan-modified extracellular vesicles and then injecting drug-loaded nanocarriers fused with CD47-enriched exosomes, lead to prolonged circulation time and increased tumor accumulation." (PMID 36918575, 2023). "Increased expression of CD47 has been observed in nearly all types of tumors, protecting tumor cells from phagocytosis and clearance." (PMID 36959204, 2023). "Targeting CD47-SIRPα promotes macrophage migration into the TME, and causes TAMs to attack tumor cells by changing TAMs from M2 to M1-like macrophages." (PMID 36721212, 2023). "Overall, SIRPα/CD47 blockade results in a therapeutic strategy for cancer treatment that involves macrophages as key players in tumor immune escape." (PMID 36829496, 2023). "Due to tumor heterogeneity, using TMA sections to evaluate CD47 tumor expression and CD68 TAM counts by IHC is a limitation of this study." (PMID 36598153, 2023). "Given that the bispecific treatment results in more favorable antitumor impacts contrasted to either SIRPα-CD47 axis or PD-1-PD-L1 axis blockade alone in mice tumor models, combined therapy with HRT and bispecific antibody warrants further investigation." (PMID 37291116, 2023). "The overexpression of CD47 has become a key strategy of the tumor cell in evading macrophage-mediated phagocytosis." (PMID 37241964, 2023). "The combination of FAO inhibitors ((e.g., the CPT1 inhibitor etomoxir) and anti-CD47 antibodies improved tumor control in a mouse model of GBM that relapsed after radiotherapy." (PMID 36778122, 2023). "Both solid and hematologic malignancies expressed higher levels of CD47, which bound with SIRPα to protect the tumor cell against macrophage-mediated phagocytosis." (PMID 38111586, 2023). "With the promising potentials of anti-CD47 blockades in cancer immunotherapy, there is ongoing interest in expanding this field in the treatment of non-neoplastic diseases." (PMID 38125492, 2023). "The high affinity of 6MW3211 to hPD-L1 and low affinity to hCD47 was supposed to navigate 6MW3211 to hPD-L1 expressing tumor cells followed by disrupting CD47/SIRPα interaction." (PMID 36593962, 2023). "designed a CD47/PD-L1 bispecific antibody, namely IBI322, that selectively binds to CD47+ PD-L1+ tumor cells to trigger intense phagocytosis of tumors by macrophages and enhance T-cell activation." (PMID 37313405, 2023). "We found that CD47, a “don’t eat me” signal that tumor cells upregulate to escape macrophage mediated phagocytosis, is highly expressed on ES." (PMID 37868989, 2023). "More importantly, CD47 is a more important “mediator” of MYC-mediated crosstalk between tumor cells and dendritic cells." (PMID 36966168, 2023). "LAT2 increases glutamine and leucine uptake in tumor cells, increasing mTORC1 signaling and Myc-dependent CD47 upregulation on tumor cells." (PMID 37380989, 2023). "Blockade of CD47 function (a universally expressed molecule in all cancers) results in tumor cell phagocytosis and elimination." (PMID 36937442, 2023). "Magrolimab is a novel humanized immunoglobulin G4 anti-CD47 antibody that improves tumor cell phagocytosis by inhibiting the binding of CD47 to SIRPα." (PMID 37894427, 2023). "Tumor suppressive activities were significantly enhanced by the dual-armed MyxV_CD47/IFN-γ compared to parental MyxV or single-armed MyxV_CD47 or MyxV_IFN-γ." (PMID 37835397, 2023).
tumor (continued). "The first feature is a consequence of numerous protein structures present on the surface of tumor cells, including the camouflaging CD47 molecule that makes tumor cells difficult to recognize by the immune system." (PMID 37895894, 2023). "It is also crucial for tumor growth, as CD47 expression on solid tumors results in evasion of the innate immune response." (PMID 36900399, 2023). "Anti-CD47 antibodies have been shown to enable phagocytosis by macrophages, induce phenotype switch from M2 to M1 TAMs and inhibit or eliminate tumor growth." (PMID 37468567, 2023). "Since then, CD47 expression has been described in various tumor types including NSCLC and SCLC, with numerous studies reporting its association with tumor stage and patient survival." (PMID 37958404, 2023). "CD47 is a transmembrane protein that is expressed on normal cells but increases in number on malignant tumour cells." (PMID 36900335, 2023). "Preclinical models validated the increase of phagocytosis and subsequent tumour growth delay by blocking the CD47/SIRP‐α axis in several blood malignancies." (PMID 37654003, 2023). "Once the anti-PD-L1 arm binds to tumor cells, the anti-CD47 arm can effectively disrupt the interaction of CD47/SIRPα and further inhibit tumor progression." (PMID 36593962, 2023). "Collectively, these results suggest that BC31M4 promotes macrophages phagocytosis of tumor cells requires both blockade of the CD47-SIRPα inhibitory pathway and activation of the Fc-mediated effector functions." (PMID 36650558, 2023). "We then assessed the impact of PARP inhibition using Olaparib on CD47 expression and CCL2 expression (known to be up-regulated by chemotherapy and recruit tumor associated myeloid cells)." (PMID 37468567, 2023). "Various tumor cells have shown decreased production of CD47 protein after treatment with JQ1 through the c-Myc pathway." (PMID 37484024, 2023). "CAP-generated ROS/RNS increase macrophage phagocytosis by suppressing the expression of the immune checkpoint CD47, and significantly improve the recognition and killing rate of NK cells against tumor cells." (PMID 37189453, 2023). "After systemic administration, they specifically and actively recognize CD47 on the tumor cell surface and simultaneously block SIRPα and CD47 on macrophages." (PMID 37012233, 2023). "Anti-CD47 significantly enhanced macrophage-mediated phagocytosis of OC cells in-vitro and exhibited potent anti-tumor activity in-vivo in OC CDX and PDX models." (PMID 37468567, 2023). "P-selectin and CD47 on PLTM enable PLTMNPs to target subcutaneous and metastatic tumors, escape phagocytosis by Mø, effectively inhibit tumor invasion and metastasis, and avoid causing hematotoxicity." (PMID 37128288, 2023). "CD47-SIRPα pathway: CD47 is an inhibitory ligand on tumor cells that binds to the signal-regulatory protein alpha (SIRPα) on macrophages, acting as a “do not eat me” signal to prevent phagocytosis." (PMID 38258072, 2023). "The blockade of CD47 with anti-CD47 or anti-SIRPα antibodies resulted in increased rates of experimental tumor eradication after RT." (PMID 37232754, 2023). "CD47 is extensively overexpressed in cancers and prevents tumor cells from phagocytosis and promotes tumor progression by activating the SIRPα-CD47 axis to avoid immune surveillance." (PMID 37580826, 2023). "The first checkpoint to be connected to tumor phagocytosis was CD47/SIRP cross-talk, commonly referred to as the don’t eat me signal." (PMID 38033495, 2023). "For example, pharmacological inhibition of this signaling pathway by anti-CD47 monoclonal antibody or by the soluble recombinant fusion protein SIRP α-FC can effectively increase TAM phagocytosis in tumor cells." (PMID 37457707, 2023). "Inhibition of the SIRPα-CD47 axis often requires the simultaneous provision of an activation signal to mark the tumor cell for destruction." (PMID 37291116, 2023).
tumor (continued). "We performed IHC analysis of CD47, p-STAT3, and p-AKT and found that CD47 levels were consistently higher in the tumor tissues than in the normal control tissues." (PMID 36413402, 2023). "Many tumor cells overexpress CD47, the prototypical “don’t eat me” signal that inhibits phagocytosis on normal cells from signal regulatory protein alpha (SIRPα)-expressing myeloid cells." (PMID 37090720, 2023). "So, phagocytosis can be enhanced by the blockade of the CD47-Signal Regulatory Protein α (SIRPα) axis using different molecules to prevent the interaction between CD47 expressed on tumor cells and SIRPα expressed on macrophages." (PMID 37175226, 2023). "Targeting of CD47 signaling is only one of several possibilities to reverse the immunosuppressive and tumor-protective tumor environment with the aim of enhancing the antitumor response." (PMID 38033495, 2023). "In fact, inactivation of one of these genes or pharmacologic bromodomain and extra terminal proteins (BET) inhibition leads to decreased CD47 expression and enhanced anti-tumor immune responses." (PMID 37468567, 2023). "Tumor cells overexpress CD47 in response to the chronic DNA damage to evade immune response, including phagocytosis." (PMID 37380989, 2023). "54% were positive for CD47 expression, yet the expression on melanocytic tumors was very low despite the low number of samples for this type of tumor (n = 4)." (PMID 36670786, 2023). "RAGA knockdown promoted LUAD tumor progression due to the accumulation of macrophage checkpoint CD47." (PMID 36823443, 2023). "The overexpression of antiphagocytic molecule CD47 on various tumor cells has made it a promising therapeutic target." (PMID 36650558, 2023). "One such potential target is CD47, a membrane protein expressed by tumor cells that prevents them from being recognized and phagocytosed by macrophages." (PMID 37626741, 2023). "Secondly, Mφ-SDNPs can scavenge CCL2 and CSF1 in the tumor site and exploit the SIRPα-CD47 interaction to remodel the tumor microenvironment." (PMID 38111068, 2023). "Although macrophages have the potential to kill tumors, tumor cells can promote tumor cell expansion and growth by binding to SIRPa on the surface of macrophages in tumor-infiltrating areas through high expression of CD47." (PMID 36627482, 2023). "Meanwhile, we should also consider that the core of the development of anti-CD47 drugs is how to kill tumor cells to the maximum extent while protecting RBCs from accidentally injure." (PMID 37171006, 2023). "These are BsAbs targeting multiple immune checkpoint receptors (such as PDL1-41BB, PD1-LAG3, and PDL1- CTLA-4) or multiple antigens in the tumor cell (such as CD47- CD19 and CD19-CD22)." (PMID 38068428, 2023). "We cultured tumor microenvironment–preserved organoids derived from surgical tumor resections of humans and treated them with anti-CD47 antibodies or isotype control." (PMID 36626230, 2023). "Immunohistochemistry staining showed significantly elevated expression of HER2 and CD47 in tumor tissues compared with adjacent tissues." (PMID 37740183, 2023). "CD47 blockade as a therapeutic strategy in non-neoplastic diseases is an emerging field of research with promising preclinical results." (PMID 38125492, 2023). "CD47/SIRPα blockade elicits anti-tumor activity by facilitating macrophage phagocytosis, which is amplified by CD40 signaling." (PMID 37345054, 2023). "In vivo experiments showed that anti-CD47 antibody (B6H12 or MIAP301) significantly inhibited the tumor growth and this effect was partly blocked by the depletion of macrophages." (PMID 37171006, 2023). "Inhibition of the CD47-SIRPα signaling pathway has also been shown to reduce the proliferation of tumor cells and accelerate the apoptosis process." (PMID 37484024, 2023). "When CD47 is inhibited, macrophages can recognize the cancer cells as foreign and phagocytose them, helping to eliminate the tumor." (PMID 38125492, 2023).